INS (insulin)
Diseases named in the same sentence as INS in open-access papers (continued):
Sharing a sentence is not in itself a finding about the gene and the disease.
diabetes (continued). "Diabetes can be caused by an imbalance or lack of insulin production into pancreatic β-cells." (PMID 36838577, 2023). "The insulin in Jr KwikPen is a rapid‐acting insulin indicated for the treatment of adults and children with diabetes who need rapid‐acting insulin in addition to long‐acting insulin for the maintenance of normal glucose levels as well as for the initial stabilization of diabetes." (PMID 37715339, 2023). "Type II diabetes mellitus (T2DM) accounts for over 90% of DM and it is typically characterized by a decrease in insulin sensitivity or insulin secretion, resulting in an increase in blood glucose levels." (PMID 37834276, 2023). "Understanding the liver-islet intercellular communication pathways and their regulation could open new avenues for developing targeted treatments to enhance insulin secretion, ultimately leading to improved glycemic control and better quality of life for individuals with diabetes." (PMID 38027137, 2023). "Diabetes mellitus (DM) is a metabolic disorder characterized by elevated blood sugar levels resulting from defects in insulin action, secretion, or both." (PMID 38107710, 2023). "Type 2 diabetes mellitus (T2 DM) is due to both an increased resistance to insulin as well as insufficient compensatory insulin secretion." (PMID 37090383, 2023). "Smart applications and systems that are designed to help individuals with diabetes manage their insulin pumps can be particularly helpful in this context, as they can provide real-time feedback and guidance on dietary choices, exercise regimens, and insulin dosing." (PMID 37174237, 2023). "Diabetes mellitus (DM) is a group of metabolic diseases characterized by hyperglycemia due to inadequate insulin secretion and/or action on target cells." (PMID 37239513, 2023). "Insulin may become necessary in patients whose uncontrolled diabetes persists." (PMID 37628857, 2023). "Diabetes mellitus (DM) is a metabolic disorder characterized by a shortage of insulin production, insulin resistance, or both." (PMID 37970376, 2023). "Furthermore, a significant presence of insulin and glucagon double‐positive cells was detected in islets of db/db mice compared to the lean control, further supporting beta cell dedifferentiation and upregulation of the alpha cell program in diabetes." (PMID 37933577, 2023). "Here, we demonstrate the protective role of insulin signaling in the gut against hepatocarcinogenesis associated with maintaining intestinal barrier function and suppressing dysbiosis using diabetic NASH-HCC model mice and samples from patients with diabetes and NASH." (PMID 37852976, 2023). "Devices for diabetes management can be broadly divided into two types, for monitoring (e.g., continuous, and self-monitoring glucose systems) and for treatment (e.g., injection devices, insulin pumps, and software, such as automatic insulin dose calculators and controllers)." (PMID 37512604, 2023). "A possible explanation for why early basal insulin therapy does not affect HRQOL in KT recipients despite having similar diabetes and hypoglycemic associated complications may be a stronger positive effect of KT itself." (PMID 37600749, 2023). "All of the mechanisms contributing to the altered limbal morphology in the diabetic rat are not known, but may include systemic inflammation caused by diabetes reducing cell replication, as well as deficiencies in insulin protection." (PMID 37304310, 2023). "A recent study reported no contribution between extra Vit D supplementation and the prevention of diabetes, while some studies suggest that Vit D, as adjuvant therapy, can effectively improve insulin sensitivity and might serve anti‐gluconeogenesis properties in obesity-related diseases." (PMID 37689713, 2023).
diabetes (continued). "Additionally, we found significant variations in several variables across the NLR tertiles, including sex, BMI, HDL-C, triglycerides, PIR, fasting glucose, glycohemoglobin, insulin use, diabetes drug use, smoking status, CVD, hypertension, ACR, eGFR, MLR, PLR, SII, SIRI, and AISI (all p < 0.05)." (PMID 38239986, 2023). "Diabetes mellitus (DM) is a chronic health disorder with hyperglycaemia resulting from insulin resistance and/or insulin inadequacy." (PMID 37358653, 2023). "Hence, older age, lower weight, longer diabetes duration, lower glomerular filtration rate (GFR) and therapies including insulin or sulfonylurea confer greater risk for hypoglycaemia and warrant special considerations about insulin dosing during hospitalization." (PMID 37173530, 2023). "Diabetes mellitus (DM) is a chronic disease that arises from either a decline in insulin synthesis (type 1 diabetes mellitus, T1DM) or a decrease in insulin sensitivity (type 2 diabetes mellitus, T2DM) that leads to hyperglycemia." (PMID 36830794, 2023). "Diabetes mellitus (DM) is a common chronic metabolic disease characterized by hyperglycemia resulting from insulin-omission." (PMID 37393287, 2023). "Diabetes mellitus (DM) comprises a group of chronic metabolic diseases characterized by chronic hyperglycemia resulting from defects in insulin secretion, insulin response, or both." (PMID 37732125, 2023). "However, to maintain homeostasis and compensate for the need for insulin to maintain glucose levels, β-cells may become depleted of their insulin pool reserves, leading to diabetes." (PMID 36992977, 2023). "In addition to these prenatal effects, postnatal malnutrition may lead to sustained impairment of insulin secretion and glucose tolerance, leading to an increased chance of diabetes prevalence later in life." (PMID 37034317, 2023). "Recent studies have reported that sleeping for too long or too short time may increase the risk of mortality in people with diabetes, especially in those diagnosed with diabetes at a young age and those with severe diabetes who receive both insulin and oral hypoglycemic drugs." (PMID 37608260, 2023). "Finally, participants Mai and Quan mentioned being “frightened” or “a little bit freaked out” as they considered their current experiences or knowledge regarding diabetes related to the need for medications (eg, insulin) or the complications of diabetes (eg, amputations and death)." (PMID 37058344, 2023). "Out of eleven patients with HG, four of them developed overt diabetes (20% of total cohort, 36% of HG cohort), still treated at the end of data collection with antidiabetic medication (oral antidiabetics in 2/4 and a combination of oral antidiabetics and insulin in 2/4)." (PMID 36824650, 2023). "An increased blood sugar level is a symptom of a range of metabolic illnesses known as diabetes mellitus (DM) that affect insulin secretion, insulin action, or both." (PMID 36846642, 2023). "Diabetes mellitus (DM) is defined as a condition of hyperglycaemia resulting from a defect in insulin secretion and/or action." (PMID 37842314, 2023). "Diabetes mellitus (DM) is a worldwide metabolic disorder defined by the presence of hyperglycemia owing to impaired insulin secretion, defective insulin action, or both." (PMID 37463968, 2023). "In the research with Diabetes Numeracy test (DNT-15) the results showed that the problems faced by patients with DM include proper calculation of insulin dosage based on current blood glucose levels and carbohydrate intake." (PMID 37726735, 2023). "However, if they have severe hyperglycemia, acute symptoms or require hospitalization, they may need insulin or follow inpatient diabetes management guidelines." (PMID 37242426, 2023). "It is reported that insulin-mediated capillary recruitment in skeletal muscles is impaired with diabetes mellitus (DM)." (PMID 37014444, 2023).
diabetes (continued). "Diabetes mellitus (DM) is “a group of metabolic diseases characterized by hyperglycemia resulting from defects in insulin secretion, resistance to insulin action, or both”." (PMID 37189437, 2023). "To assess whether the dysbiosis observed in STAM mice, presumably due to decreased insulin action in the gut, was also relevant to patients with diabetes and NASH, we performed 16 S metagenomic analyses using fecal DNA samples of patients comorbid with diabetes and NASH." (PMID 37852976, 2023). "Diabetes mellitus is a major cause of mortality worldwide and type I diabetes mellitus (T1DM) is characterized as a chronic metabolic disorder caused by autoimmune dysfunctions that destroy the mass of insulin-producing cells, known as β-cells, in the pancreas, thus inducing severe hyperglycemia." (PMID 37644502, 2023). "In conclusion, although robust evidence endorses the involvement of p66Shc in pancreatic beta-cell failure and loss, the findings on insulin sensitivity, glucose tolerance, glucose uptake, and metabolism have not been conclusive, questioning the role of p66Shc in diabetes induction and progression." (PMID 38203279, 2023). "Thus, to appropriately control diabetes, it is necessary to optimize the diet of each patient in terms of the quantity and type of food, the pattern of food consumption during the day, and exogenous insulin administration." (PMID 37089422, 2023). "Moreover, apelin levels in insulin-resistant disorders, namely obesity, and T2DM, are increased, and apelin treatment increases insulin sensitivity, glucose tolerance, and fatty acid oxidation, representing the effectiveness of exogenous apelin on diabetes-related complications." (PMID 37424869, 2023). "The results of the present study showed that FE G in both parents significantly (mail: p < 0.0001, female p < 0.001) decreased after diabetes induction and Mg or insulin administration could significantly increase FE G in both sexes (male: p < 0.0001, female: p < 0.001) in compared to DC groups." (PMID 36755074, 2023). "In contrast, 2-AAA was associated with higher insulin in individuals with and without diabetes." (PMID 37745703, 2023). "Also, blood insulin test may have cross‐reactivity with exogenous insulin in patients with diabetes who take insulin." (PMID 36808709, 2023). "Diabetes mellitus (DM) is a multi-factorial disease, characterized by uncontrolled blood glucose levels due to shortcomings in insulin production and/or its function." (PMID 36615587, 2023). "Diabetes is a global health problem caused by a lack of insulin or insulin resistance." (PMID 36816302, 2023). "In a clinical trial that included SGLT2 inhibitors together with basal insulin and metformin as an intensive intervention, the group receiving SGLT2 inhibitors saw higher rates of remission than the traditional group (24.7% vs. 16.9%), and their risk of diabetes recurrence was cut by 43%." (PMID 36819346, 2023). "Given the patient’s mother was diagnosed with diabetes in her mid-forties and transitioned to insulin-based therapy 5 years post-diagnosis, ongoing monitoring of the patient, their sibling, and children for changes in blood glucose, insulin resistance, and pancreatic function is crucial." (PMID 38333726, 2023). "In our study, when patients with a diagnosis of diabetes were evaluated, it was noted that the majority of them were using metformin, as monotherapy or in combination with sitagliptin, or insulin, and we assume that the lower levels of IL-18 and hsCRP might be related to this treatment." (PMID 37763063, 2023). "When considering specific combinations of medications (ranging from no drugs to oral agents to insulin) as proxy indicators of severity of diabetes, diabetes was associated with a reduced risk of death compared to non-diabetics across all strata of diabetes severity (Page 15)." (PMID 36570973, 2023).
diabetes (continued). "On the other hand, diabetes leads to higher levels of inflammatory markers and higher rates of nitric oxide release in women than in men, resulting in reduced protective effects of estrogen on body fat distribution, insulin action, and more impaired endothelial function." (PMID 36839318, 2023). "The World Health Organization describes diabetes mellitus as a metabolic disorder of diverse etiology, characterized by chronic hyperglycemia with disturbances in protein, carbohydrate and fat metabolism, resulting from impaired insulin action, insulin secretion or both." (PMID 37606477, 2023). "In the current work, we have linked the dysregulation and mistargeting of the diabetes executer protein VDAC1 to the suppression of GPR56, thereby linking this adhesion GPCR to β-cell mitochondrial dysfunction with impaired ATP accumulation and compromised insulin secretion." (PMID 36979492, 2023). "Diabetes mellitus (DM) is defined as a group of metabolic derangements that are characterized by compromised insulin synthesis or function, which eventually results in hyperglycemia." (PMID 36768255, 2023). "Experiments on mouse models of diabetes have shown that treatment of mice with a pan-Hsp90 inhibitor and also knockdown of HSP90ab1 have been found to improve glucose homeostasis and insulin sensitivity, suggesting a role of these chaperones in the pathogenesis of type diabetes." (PMID 37569434, 2023). "Thus, BET overexpression could be an innovative strategy for inducing β-cell regeneration and an alternative to insulin injections by increasing the number of endogenous insulin-producing cells in patients with diabetes." (PMID 37108631, 2023). "Treatment options for diabetes may range from oral medication to insulin treatments." (PMID 37055503, 2023). "Likewise, data from over 110 observational and clinical trials suggest that dietary patterns similar to a WFPBD are associated with a decreased presence of diabetes and significant improvements in biochemical profiles, including total LDL, and therapeutic requirements, for insulin in particular." (PMID 37469546, 2023). "Moreover, studies have suggested that PF4 levels are elevated in DKD, with PF4 levels in insulin-dependent patients with diabetes with substantial albuminuria being significantly elevated compared to those in patients with diabetes with mild albuminuria and healthy controls." (PMID 37834171, 2023). "Finally, some patients with diabetes mellitus may have taken antidiabetic drugs or injected insulin at the time of blood sample collection." (PMID 37334918, 2023). "Diabetes mellitus (DM) is a metabolic disorder characterized by persistent hyperglycemia due to insufficient insulin secretion or impairment of islet function, which is now one of the major threats to human health in the 21st century." (PMID 37687255, 2023). "Despite having sufficient insulin, an individual may have a higher FBG value which is mainly due to insulin resistance which is the commonest cause of impaired fasting glucose tolerance and diabetes mellitus." (PMID 38124783, 2023). "A case-control study involving individuals with diabetes highlighted that long-term use of metformin was associated with a slight increase in AD risk, whereas long-term use of sulfonylureas, thiazolidinedione, or insulin was not." (PMID 37508448, 2023). "The management of diabetes mellitus (DM) has been vastly improved due to the broader access to technological devices such as glucose sensors (GS) and continuous subcutaneous insulin infusion (CSII) sets." (PMID 37445875, 2023). "The similarities in PedsQL questionnaire scores amongst the two groups show that for youth with T2D that use insulin, the impact of diabetes on QoL may be comparable to youth with T1D, attributable to a similar burden of management and the experience of similar lifestyle interruptions." (PMID 40303266, 2023).
diabetes (continued). "In contrast, the majority of citations for studies evaluating the metabolic effects of curcumin in insulin-resistant populations with obesity (26% of studies in this category), metabolic syndrome (15%), or type 2 diabetes mellitus (26%) reported positive outcomes for commonly studied endpoints." (PMID 36901908, 2023). "Uncontrolled diabetes can result in serious consequences like diabetic nephropathy (kidney dysfunction), pancreatic inflammation (leading to persistent hyperglycaemia), liver damage (cirrhosis and liver failure), inflammatory gut, and insulin resistance in liver and skeletal tissue." (PMID 37434784, 2023). "Diabetes mellitus (DM) is one of the endocrine disorders that affect the body's capability to produce or use insulin." (PMID 37529488, 2023). "However, in our study, it was confirmed that the patient’s characteristics—preservation of insulin secretion at baseline and newly diagnosed diabetes—may be more important than the effect of kidney transplantation itself on glucose metabolism." (PMID 37424863, 2023). "Diabetes mellitus (DM) summarizes a group of metabolic disorders having in common elevated blood glucose levels (hyperglycemia) and insufficient insulin production and/or action." (PMID 38003446, 2023). "Diabetes mellitus (DM) is a chronic metabolic disorder characterized by elevated blood glucose levels resulting from inadequate insulin production." (PMID 37415097, 2023). "Diabetes mellitus (DM) is a metabolic disorder characterized by hyperglycaemia due to defects in insulin secretion, insulin action, or both." (PMID 36860368, 2023). "The study demonstrated the ability of the JAK inhibitor to correct abnormalities in insulin signaling in the liver and skeletal muscle, shedding further light on the pilot role of JAK2 in the regulation of different metabolic processes implicated in the development of diabetes and obesity." (PMID 37701031, 2023). "After adjustment for potential confounders, including co-morbidities, glycemic control and concomitant treatments, we found that diabetes on insulin was associated with a 2.2-fold higher risk of ischemic stroke/TIA/systemic embolism vs no diabetes or diabetes not on insulin." (PMID 35976428, 2023). "B lymphocyte-depleted individuals had a delayed decline of endogenous insulin production, measured by C-peptide, and B cell depletion therapy in mouse models has both provided protection from diabetes when administered in prediabetic mice and reversed diabetes when administered after diabetes onset." (PMID 37731505, 2023). "Diabetes mellitus (DM) is a long-standing, continuously growing metabolic ailment in which levels of glucose in the blood increase due to a total (DM of type 1) or incomplete (DM of type 2) decrease in the level of the hormone insulin." (PMID 37546053, 2023). "Thus, the combination of impaired secretion of glucagon and non-physiological distribution of injectable insulin contributes to a higher risk of hypoglycaemic events and long-term micro- and macrovascular complications in diabetes patients." (PMID 36404376, 2023). "GLIS3 might control insulin gene transcription and played a role in insulin secretion in β cells, while deficiency of GLIS3 induced apoptosis of the β cells of pancreatic islets and caused diabetes." (PMID 38087213, 2023). "Plant polysaccharides can also stimulate insulin secretion, modulate the activity of glucose metabolizing enzymes, inhibit the gluconeogenesis pathway, and promote glucose utilization in peripheral tissues, thus performing important functions in the prevention and treatment of diabetes." (PMID 37293228, 2023). "A keyword search was conducted by using search terms for humans (night shift, glucose insulin, circadian, and misalignment’), rodents (circadian, circadian rhythm, diurnal, rodent, metabolism, diabetes, and high-fat), and cell biology (circadian rhythm, diurnal, diabetes, and hepatocytes)." (PMID 37642240, 2023).